CXCR3 (C-X-C motif chemokine receptor 3)
Diseases named in the same sentence as CXCR3 in open-access papers (continued):
Sharing a sentence is not in itself a finding about the gene and the disease.
ovarian carcinoma (continued). "In ovarian cancers, we found that CXCL11-CXCR3-A/CXCR3-alt axes are increased and that CXCL4-CXCR3-B axis is decreased in ovarian cancers." (PMID 24213462, 2012). "In contrast to prior reports demonstrating induction of CXCR3 chemokines upon immune checkpoint inhibition in preclinical models other than ovarian cancer, we did not observe such an increase in the ID8 ovarian cancer model." (PMID 35314795, 2022). "Expanding prior reports already suggesting involvement of CXCR3 chemokines in the ICB mechanism of action, our study is, to the best of our knowledge, the first to demonstrate that CXCL9 is all by itself sufficient to overcome ICB resistance in ovarian cancer." (PMID 35314795, 2022). "Furthermore, migration was shown to be inhibited by an anti-CXCR3 antibody in both ovarian cancer cell lines, SKOV-3 and OVCAR, as well as ovarian cancer samples derived from metastatic sites." (PMID 34440489, 2021). "In this study, it was found that CXCR3 was highly expressed in ovarian tumor tissues and expressed in different degrees in different types of ovarian cancer, but it was not related to clinical stage." (PMID 33829065, 2021). "In ovarian cancer, These ELR− chemokines share a common receptor CXCR3." (PMID 24213462, 2012).
multiple sclerosis (32 papers, 2006 to 2025). A progressive autoimmune disorder affecting the central nervous system resulting in demyelination. "CXCR3 has been implicated in several pathologically relevant diseases, including multiple sclerosis, pulmonary fibrosis, type 1 diabetes, and acute heart transplant rejection." (PMID 40648816, 2025). "Specifically, recent work has reported an association between EBV infection and a neuroinvasive, pathogenic subset of T-bet+/CXCR3+ B cells identified within clinically isolated syndrome (CIS)/multiple sclerosis (MS) patients." (PMID 36248899, 2022). "In the brain, CXCR3-expressing cells have been implicated in Alzheimer’s disease and other age-dependent cognitive dysfunctions, multiple sclerosis, epilepsy, and stroke." (PMID 39535032, 2024). "Previous studies have shown that CXCL11/CXCR3 expression is significantly upregulated in many CNS diseases, such as cerebral ischemic stroke and multiple sclerosis." (PMID 39315097, 2024). "CXCR3 is abundantly expressed on CNS-infiltrating T cells in multiple sclerosis patients and coordinates CNS-directed T cell migration in response to its three ligands, CXCL9/CXCL10/CXCL11." (PMID 38349430, 2024). "CXCL10 is a multiple sclerosis (MS)-relevant chemokine that is present in the injured central nervous system and recruits CXCR3+ immune cells toward injured tissues." (PMID 37627269, 2023). "CXCL10 is also strongly upregulated in many other autoimmune and inflammatory diseases like multiple sclerosis and allograft rejection, resulting in the accumulation of CXCR3+ T cells." (PMID 34481469, 2021). "CXCL10 and its receptor CXCR3 play a critical role in multiple sclerosis, particularly in leukocyte recruitment into the CNS." (PMID 20186338, 2010). "CXCR3 is highly expressed in cerebrospinal fluid (CSF) leukocytes, and its ligand CXCL10 is upregulated in the CSF of multiple sclerosis patients, suggesting that CXCR3 may play an important role in the chemotaxis of cells to CNS." (PMID 33743810, 2021). "Separately, de novo EBV infection led to the development of CXCR3+/CD11c+/FCRL4+ B cells within days, providing evidence for possible T cell-independent origins of a recently described EBV-associated neuroinvasive CXCR3+ B cell subset in patients with multiple sclerosis." (PMID 36248899, 2022). "Assessing 15 representative signature genes in patients with multiple sclerosis, we find that TH1/17 cells have elevated expression of CXCR3 and reduced expression of IFNG, CCL3, CLL4, GZMB, and IL10 compared to healthy controls." (PMID 29150604, 2017). "CXCR3-positive T cells are increased in the blood of patients with multiple sclerosis (MS), and its ligand CXCL10 is expressed by astrocytes in MS brain lesions, suggesting that CXCR3 may be involved in the immune response and lesion development in MS." (PMID 40786052, 2025). "Expression of CCR2, CXCR3 and CCR4 on CD4+ T or CD8+ T cells in blood and cerebrospinal fluid (CSF) for multiple sclerosis (MS) was measured by 3-color flow cytometry, and compared to blood from healthy controls and CSF from patients with other inflammatory neurological diseases (INDs)." (PMID 19662226, 2007).
atherosclerosis (30 papers, 2008 to 2025). A disease characterized by the build-up of fatty material and calcium deposition in the arterial wall resulting in partial or complete occlusion of the arterial lumen. "In mouse disease models, antibodies or small molecule antagonists of CXCR3 have been shown to significantly delay the progression of diseases such as atherosclerosis, transplant rejection, and cancer, making CXCR3 antagonists a key focus in drug discovery." (PMID 40786052, 2025). "CXCR3 plays a key role in cardiovascular diseases, such as atherosclerosis, cardiac hypertrophy, heart failure, cardiac transplant rejection, and myocardial infarction, through its interaction with various ligands." (PMID 40786052, 2025). "The results indicated that compared with arthritis mice (+ K/BxN serum −HFD), arthritis mice combined with atherosclerosis (+ K/BxN serum + HFD) significantly increased the CD3+/CXCR3+ cells (P < 0.05), CD68+ macrophages (P < 0.001), CD3+ T cells (P < 0.05)." (PMID 39716053, 2024). "[18F]1 was further evaluated for reliability as a CXCR3 radiotracer using mouse models of atherosclerosis." (PMID 36865232, 2023). "Atherosclerosis can shift Tregs from a protective CXCR3+Treg response to dysfunctional interferon (IFN) γ+Th1/Treg response, driving inflammation and worsening disease progression." (PMID 36911741, 2023). "In atherosclerosis-prone mice, the atherogenic environment enhanced the autoimmune responses of CXCR3+ Tfh cells." (PMID 35769488, 2022). "Several reports implicate CXCR3 and its ligands in the etiologies of various cardiovascular diseases, including atherosclerosis, hypertension, heart failure, and myocardial infarction." (PMID 35794867, 2022). "Research confirmed that ANW downregulated the expression of chemokine receptors CCR2, CXCR3, and cell adhesion molecules in the arterial vasculature and alleviated the development of atherosclerosis by suppressing inflammation." (PMID 35388303, 2022). "The two inflammatory receptors CXCR2 and CXCR3 have also been widely involved in the pathogenesis of atherosclerosis." (PMID 34440065, 2021). "The present review focuses on the role of the IFN-γ inducible chemokines and their receptor CXCR3 in the development of atherosclerosis and consequent coronary artery disease." (PMID 30210493, 2018). "A relationship between CXCR3 and atherosclerosis, type I diabetes, and acute cardiac allograft rejection has also been shown in previous studies." (PMID 25343742, 2014). "Of note, within the TEM subsets, we have identified subpopulations with a strong correlation with the extent of atherosclerosis, such as those expressing HLA-DR, CXCR3, and CCR5." (PMID 23130116, 2012). "In atherosclerosis, CXCR3 and its ligands influence plaque formation and rupture." (PMID 40786052, 2025). "Chemokine-receptor profiling in T1D group was marked by a positive association between CCR2+ monocytes and CCR4+ T lymphocytes with DBP, as well as between CCR2+ and CXCR3+ B lymphocytes with TG, linking endothelial inflammation, atherosclerosis and dyslipidemia." (PMID 39109081, 2024). "Taken together, [18F]1 is a potential PET radiotracer for imaging CXCR3 in atherosclerosis." (PMID 37438543, 2023). "[18F]1 was validated as a CXCR3 PET radiotracer using mouse models of atherosclerosis." (PMID 36865232, 2023). "Therefore, detection of CXCR3 by positron emission tomography (PET) radiotracer can be a useful tool for detecting the development of atherosclerosis in a noninvasive manner." (PMID 37438543, 2023). "CXCR3 is a chemokine receptor which is has primarily been studied in atherosclerosis in the context of T cells and NK cells, with Th1 cells expressing high levels of CXCR3 seen in atheroma and CXCR3 knockout mice having reduced atherosclerotic burden and lower levels of infiltrating T cells." (PMID 37927302, 2023). "Taken together, [18F]1 is a potential PET radiotracer for the imaging of CXCR3 in atherosclerosis." (PMID 36865232, 2023).
atherosclerosis (continued). "Sc-RNA-seq research found a higher CXCR3 expression level in circulating CD4+ T cells in symptomatic atherosclerosis patients compared to asymptomatic atherosclerosis patients, indicating that these cells can be activated and recruited into plaques to aggravate the disease." (PMID 36685487, 2022). "CD8+ T cells express higher levels of CXCR3 in patients with symptomatic atherosclerosis." (PMID 36045343, 2022). "Similarly, genetic depletion of Cxcr3 or antagonizing CXCR3 pharmacologically in mice reduced atherosclerosis progression and infiltration of inflammatory T cells, while Treg numbers rised." (PMID 35087886, 2021). "Genetic inactivation of Cxcr3 or its ligand Cxcl10, that were both detected in mouse lesions in the ApoE−/− strain, resulted in decreased atherosclerosis burden that was accompanied by a decrease in inflammatory CD4+ T cell content, an elevated number of Tregs, and increased expression of IL-10." (PMID 24741577, 2014). "Therefore, the detection of CXCR3 by positron emission tomography (PET) radiotracer may be a useful tool to detect atherosclerosis development noninvasively." (PMID 36865232, 2023). "Since CXCR3 involvement is at the onset of this disease, detailed investigation into the receptor acting as a therapeutic target could have implications towards blocking the progression of atherosclerosis." (PMID 35794867, 2022). "Given the potential association between TEM and atherosclerosis and to further investigate whether any of the TEM subpopulations could better explain this finding, the correlation between CXCR3+TEM, CCR5+TEM, HLA-DR+TEM subpopulations, and IMT was investigated." (PMID 23130116, 2012). "In an arterial graft transplantation model that induced atherosclerosis, the administration of neutralizing antibodies against CCL21 and CXCR3 suppressed TLS formation and prevented the progression of atherosclerosis." (PMID 41029827, 2025). "CXCR3 chemokines (including MIG, IP-10, and I-TAC) may play a decisive role in developing atherosclerosis." (PMID 35345521, 2022). "As TEM are antigen-experienced and long-surviving cells that have lost CCR7 and express HLA-DR, CXCR3, and CCR5, this finding strengthens the concept that the understanding of the inflammatory pathogenesis of atherosclerosis requires careful cellular subphenotyping." (PMID 23130116, 2012). "In addition, various immune-related genes have been examined in an atherosclerosis animal model, and genes such as CXCR6, CXCL10, CXCR3 and CXCL16/scavenger receptor have been shown to be involved in the progression of atherosclerosis in animal models." (PMID 18673543, 2008). "Compared with normal mice (−K/BxN serum -HFD), the populations of CD3+/CXCR3+ cells, CD68+ macrophages, CD3+ T cells of atherosclerosis mice (−K/BxN serum + HFD) did not exhibit any significant differences." (PMID 39716053, 2024).
colitis (30 papers, 2008 to 2024). Inflammation of the colon. "CXCR3 deficient mice have shown to be resistant to dextran sulfate sodium-induced colitis, highlighting the role of this pathway in the development of colitis." (PMID 34777387, 2021). "We showed that the deficiency of CXCR3 led to opposite outcomes for the severity of autoimmune cholangitis and colitis." (PMID 29868034, 2018). "The present study explores the CXCR3 axis and cellular mechanisms that drive Mycobacteria-associated colitis in IL-10-/- mice." (PMID 18533024, 2008). "As with these innate immunity cells, neutrophils are compartmentalized in the MLN and tightly regulated to differentially express CXCL9 and CXCL11, CXCR3 and Th1-associated cytokines during Mycobacteria-mediated colitis." (PMID 18533024, 2008). "However, our data showed different expression patterns of CXCR3 and PD-1 on the pathogenic T cell subsets for colitis and cholangitis, the colon CD4+ T cells and the hepatic CD8+ T cells, respectively." (PMID 29868034, 2018). "For the opposite disease severity, we speculate the differentiation of CD8+ T cells was the main cause for aggravated cholangitis with second decreased Th17 response, while the decreased Th17 response was important for alleviated colitis after CXCR3 deficiency in CD25−/− mice." (PMID 29868034, 2018). "In the CD25−/− mice, we detected high levels of CXCR3 expression on T cells from the liver and MLN as well as increased levels of CXCR3 ligands, indicating that the CXCR3 pathway is involved in regulating autoimmune cholangitis and colitis in this mouse model." (PMID 29868034, 2018). "Taken together, these results indicate that in this mouse model for autoimmune cholangitis and colitis, expression of CXCR3 and its ligands are increased in the liver and colon." (PMID 29868034, 2018). "Surprisingly, the colitis of CD25−/− mice was alleviated after CXCR3 deletion, which was indicated by H&E staining of colon, score of colitis (p = 0.0328), and colon weight (p = 0.0027)." (PMID 29868034, 2018). "Herein, we found different changes of Th1 and Th17 responses after CXCR3 deletion in both cholangitis and colitis, in which they resulted in opposite changes to the disease severity." (PMID 29868034, 2018). "Previous studies from our laboratory suggest that T cells expressing CXCR3, a chemokine results in development of colitis." (PMID 30024891, 2018). "For the past 15 years our laboratory has worked on this chemokine and have shown that CXCR3 and its ligands are upregulated at sites of experimental colitis." (PMID 29707158, 2018). "To explore the role of CXCR3 in cholangitis and colitis, we crossed CD25+/− mice with CXCR3−/− mice to generate CD25−/−CXCR3−/− mice." (PMID 29868034, 2018). "This study demonstrated attenuated DSS-induced colitis in CXCR3−/− mice at both the macroscopic and microscopic level." (PMID 24992040, 2014). "Taken together, our findings demonstrate significantly attenuated DSS-induced colitis in the CXCR3 KO mice." (PMID 24992040, 2014). "Deficiency of CXCR3 alone has been associated with the effective reduction of colitis via reduced monocyte and neutrophil infiltration, ameliorating DSS-induced colitis, thereby making CXCR3 an attractive target for reducing inflammation." (PMID 24992040, 2014). "We found a significant increase in the percentage of splenic, MLN and LP CD4+T cells that expressed CXCR3+ during DSS induced colitis, which was reversed following TCDD treatment." (PMID 21858153, 2011). "Taken together, these results suggested that TCDD ameliorates acute colitis by increased generation of Tregs in the LP of mice with colitis, with consequent decrease in CXCR3+ T cell expression." (PMID 21858153, 2011). "CXCR3+ T cells are activated and recruited into inflammatory sites by CXCL10 and have been previously associated with colitis in mice." (PMID 20360984, 2010).
colitis (continued). "Mycobacteria-challenged IL-10-/- mice housed under otherwise pathogen-free conditions develop colitis that is driven by CXCR3- and corresponding ligand(s)-expressing leukocytes, which underscores another important hallmark or molecule mechanism of colitis." (PMID 18533024, 2008). "Together, the data show that Mycobacteria-dependent host responses, namely CXCL10+ T cells and NK cells, assist in the recruitment and activation of CXCR3+ and CXCL11+ leukocytes to enhance colitis of susceptible hosts." (PMID 18533024, 2008). "The current study suggests NK and NKT cells collaborate to produce CXCL10, IL-12p40, TNF-α, and IFN-γ to recruit and stimulate CXCR3+ leukocytes in either inductive or effector sites during colitis." (PMID 18533024, 2008). "Previous data have shown that CXCR3 expression in peripheral Tregs inhibits the immune response and systemic inflammatory cytokines, thereby reducing inflammation and leading to effective inhibition of colitis." (PMID 35813827, 2022). "In the IL-10−/− colitis mouse model, CXCR3 was found highly expressed in the gut." (PMID 32503584, 2020). "Deletion of CXCR3 resulted in enhanced liver inflammation but alleviated colitis." (PMID 29868034, 2018). "CXCR3 plays an important role in recruiting pro-inflammatory cells, specifically neutrophils, in a model of sterile colitis whereby CXCR3−/− mice showed an attenuated course of colitis with markedly reduced host-tissue damage in the inflamed caecum." (PMID 28860493, 2017). "Overall, our results suggest that CXCR3 plays an important role in recruiting proinflammatory cells to the colon during colitis and that CXCR3 may be a therapeutic target to reduce the influx of proinflammatory cells in the inflamed colon." (PMID 24992040, 2014). "Although our DSS model of colitis is representative of acute inflammation, it is possible that the role of CXCR3 in chronic colitis may be mediated by IFN-γ as demonstrated in other chronic models of inflammation, to which further investigations is required." (PMID 24992040, 2014). "Leukocyte infiltration mediated by CXCR3 in colitis development is not well understood." (PMID 24992040, 2014). "We hypothesised that CXCR3 KO mice would have impaired cellular trafficking, thereby reducing the inflammatory insult by proinflammatory cell and attenuating the course of colitis." (PMID 24992040, 2014). "Our results also suggested that the increase in the number of mucosal CXCR3+ T cells seen during acute colitis could be mitigated by TCDD treatment." (PMID 21858153, 2011). "In conjunction with an abundance of effector T cell responses, myeloid cells in ICI-colitis also display an inflammatory gene signature enriched in TNF-α- and IFNγ-inducible elements such as CXCL16, CXCL9 and CXCL10, which encode chemokines that attract CXCR6+ and CXCR3+ T cells, respectively." (PMID 39247203, 2024). "However, in the context of intracellular bacteria-induced colitis, CXCR3 seems to be crucial in mounting an efficient immune response to limit and clear salmonellosis, which may be due to host response to different pathogenic challenges." (PMID 28860493, 2017). "Although a previous study has reported attenuated DSS-induced colitis by simultaneous blockage of chemokine receptors CCR2, CCR5 and CXCR3, we demonstrate that CXCR3-deficient (KO) mice alone challenged with dextran sulfate sodium (DSS) are resistant to the development of experimental colitis." (PMID 24992040, 2014). "We determined the frequencies of Tregs (CD4+FOXP3+), Th1 cells (CD4+CXCR3+), and Tfh cells (CD4+CXCR5+) in the colonic lamina propria in DSS-induced colitis." (PMID 38396052, 2024). "Concomitant with colitis development, DCs in inflamed patients increase in number and upregulate the expression of CCR7, TNF, and CXCR3 costimulator molecules." (PMID 35813827, 2022). "As in arthritis-irAE, CXCR3 and CXCR6 were suggested to play a key role in recruiting T cells into colitis-irAE sites." (PMID 35413951, 2022).